TNF (tumor necrosis factor)
Diseases named in the same sentence as TNF in open-access papers (continued):
Sharing a sentence is not in itself a finding about the gene and the disease.
Sepsis (continued). "Since MCP-1/CCL2 shows a protective role in a similar mouse model (a polymicrobial sepsis model with LPS), DAG-deepVASE suggests a therapeutic potential to the detrimental interaction between IFN-γ and TNF-α." (PMID 37395630, 2022). "A large number of pro-inflammatory factors, such as TNF-α, IL-1β, and IL-6, and endotoxins can act on the BBB and then increase permeability in the process of sepsis." (PMID 36552192, 2022). "In a prospective study including 68 newborns with early-onset sepsis (EOS) and 83 newborns as a control group, it was demonstrated that IL-6, TNF-α, HSP70, PCT, and CRP together with MMP-8 can be used as a predictive biomarker of EOS." (PMID 36613805, 2022). "We investigated the effects of lipopolysaccharide-induced sepsis on novel object recognition test, NGAL levels, an inflammatory mediator tumor necrosis factor-α (TNFα) levels, and iron ion levels in the hippocampus and cortex of young and aged rats." (PMID 34997032, 2022). "In comparison to mild sepsis (SOFA <10), genes in neutrophils were significantly enriched in biological pathways such as TNF-α signaling via NFKB, Interferon-γ, and Interferon-α response." (PMID 36304125, 2022). "After the sepsis model was established using the CLP method, the serum contents of CORT, IL-6, TNF-α, CRP, and sICAM-1 in the model group were substantially increased compared to those of the control group." (PMID 36338128, 2022). "Our study found that SD can alleviate sepsis-induced ALI by inhibiting the NF-κB signaling pathway and reducing the level of TNF-α in BALF." (PMID 36526959, 2022). "Mice treated with LR17 had decreased sepsis severity demonstrated by lower levels of IL-6, TNF-a, and IL-10 in serum, peritoneal and bronchoalveolar fluid, and IL-6 and TNF-a in the liver, and lung." (PMID 35784361, 2022). "Cytokines including interleukin- (IL-) 1, IL-6, tumor necrosis factor-α (TNF-α), interferon (IFN) regulatory factor 7 (IRF7), and adaptor protein 1 (AP-1) are produced after activating of PRRs during sepsis." (PMID 36062193, 2022). "Compared with those in the sepsis group, the levels of IL-6, IL-1β and TNF-α were decreased (P < 0.05), the MDA content was decreased, with the SOD and CAT activities increasing in the sepsis + DMOG group (P < 0.05)." (PMID 35576220, 2022). "BPF treatment indeed inhibited the CLP-induced production of IL-6, TNF-α, and CXCL1 by sepsis-induced peritoneal macrophages (consistent with the results in HUVECs and THP-1-macrophages)." (PMID 36361915, 2022). "There was a clustering of CXCL8, TNFα, CCL4, CCL3, IL-1β and IL-6in the sepsis group indicating a chronic inflammatory response which seems to be mediated mostly by monocytes, whereas the febrile controls had no specific pattern." (PMID 35811678, 2022). "Regarding pro-apoptotic genes, sepsis increased mitogen activated protein kinase 14 (MAPK14) in OVR females and tumor necrosis factor- α (TNF-α) in control females." (PMID 35322092, 2022). "Third, concentrations of TNF in sepsis are comparable to levels observed in common non-lethal diseases like rheumatoid arthritis, inflammatory bowel disease, and Streptococcal pharyngitis, casting further doubt that sepsis-associated inflammation causes sepsis (manuscript in preparation)." (PMID 35814227, 2022). "More importantly, we observed that the plasma TNF-α in patients with T2DM and sepsis carrying the rs1024611 GG genotype was upregulated with MCP-1." (PMID 35960063, 2022). "Studies have shown that XBJ mainly inhibits the activation of inflammatory pathways by inhibiting TNF-α, IL-1, IL-6, IL-8, IL-17 and PAR-1 and improves coagulation dysfunction in sepsis." (PMID 35648739, 2022). "In the sepsis+SO2 group, levels of TNF-α in plasma and lung tissue were reduced, and the oxidative stress index was significantly improved compared with the sepsis group." (PMID 35265263, 2022).
Sepsis (continued). "In human sepsis, MHC II (HLA-DR) antigen expression is commonly used as a marker of immunosuppression, as it correlates with TNF production by the monocytes as well as the clinical course and development of secondary infections." (PMID 35566768, 2022). "Treatment of mice with general S1PR agonist FTY720 and S1P lyase inhibitor 4-deoxypyridoxine before inducing sepsis by peritoneal contamination and infection (PCI) reduced microvascular leakage in lung and liver, and dampened IL-6, TNFα, and MCP-1 production." (PMID 35634305, 2022). "Endothelial inflammatory activation in sepsis can occur via recognition of bacterial products such as LPS by TLR4 and RIG-I, or through pro-inflammatory cytokines including TNFα produced by immune cells." (PMID 35634305, 2022). "Corticosteroids are appealing agents due to their broad anti-inflammatory effects against cytokines such as Interleukin (IL)-1, IL-2, Tumor Necrosis Factor (TNF)-α, and IFN-gamma, which can lead to sepsis and respiratory failure." (PMID 35991665, 2022). "In this study, we investigated the effects of LPS-induced sepsis on object recognition and brain NGAL, TNFα, and iron ion levels in aged and young survivor rats." (PMID 34997032, 2022). "Earlier studies have investigated the effect of blockading inflammatory cytokines such as TNF-α, and others have looked at the effect of inhibiting COX-2 activity against sepsis." (PMID 35884918, 2022). "Next, we measured the level and fold change of sepsis biomarkers such as DNI, MPO, PCT, and TNF-α at baseline, 6 h, 24 h and 48 h post-CLP." (PMID 35334545, 2022). "Intraportal injection of norepinephrine at a concentration under septic conditions increased circulating interleukin (IL)-1β and tumor necrosis factor (TNF)-α, similar to that found in sepsis." (PMID 36552603, 2022). "lncRNA CRNDE was upregulated in patients with sepsis and SA-AKI models, and CRNDE overexpression markedly boosted inflammatory cytokine levels, including TNF-α, IL-6, IL-8, and IL-1β." (PMID 35464083, 2022). "In the resveratrol-treated sepsis rats (100 mg/kg, ip), the levels of MDA and TNF-α were lower while the level of reduced glutathione (GSH), SOD, and GPX activities were higher compared to septic group." (PMID 36588685, 2022). "The sepsis-induced activation of p38 MAPK was paralleled by a massive increase in the systemic levels of proinflammatory cytokines, such as TNF-α, IL-1β, IL-17 and IL-6, as well as the anti-inflammatory cytokine IL-10." (PMID 35178052, 2022). "Circulating cardiac depressant factors such as tumor necrosis factor α (TNF-α), interleukin (IL)-6, IL-1β, NO, bacterial RNA and DNA, and lysozyme C have also been described in sepsis." (PMID 35706715, 2022). "During sepsis, casp-8 can be activated by signaling complex via death receptors, like FAS ligand or TNF-α." (PMID 35190789, 2022). "Carnosine renormalized lipid peroxidation, reduced the level of IL-β, tumor necrosis factor-alpha (TNF-α), and macrophage inhibitory factor (MIF), thus demonstrating a beneficial effect in sepsis." (PMID 34203479, 2021). "The results showed that sIL-2R, TNF-α, and PCT in the sepsis group were significantly higher than those in the infection group, which was consistent with previous studies on infectious diseases." (PMID 34745113, 2021). "The present study, which compared patients with sepsis alone vs. sepsis and ARDS, identified much higher levels of serum FGF21 and pro-inflammatory factors (PCT, CRP, IL-6, and TNFα) in the Sepsis + ARDS group." (PMID 34154595, 2021). "Procalcitonin compared to IL-2, IL-6, IL-8 and TNF-α also has the highest sensitivity and specificity for differentiating patients with SRIS from those with sepsis." (PMID 34577795, 2021). "By 4 h p.i., 7 additional cytokines were significantly reduced, including TNF, IL-6, and CXCL1 (KC) which have major roles in sepsis pathogenesis." (PMID 34873199, 2021).
Sepsis (continued). "We evaluated the plasmatic release of TNFα and CXCL2/3 in wild-type animals during polymicrobial sepsis to strengthen our findings." (PMID 34948374, 2021). "Thirty hours after induction of sepsis, testicular samples were collected to measure SOD activity and MDA, IL-6, and TNF-α levels." (PMID 35317115, 2021). "It was found that the expressions of TNF-α, IL-1β, IL-6 in CLP group were significantly increased (P < 0.001), suggesting that animal’s inflammatory response was activated by sepsis." (PMID 34565302, 2021). "Moreover, transfection of miR-30c-5p mimic had the potential ability to suppress on the level of TNF-α and IL-6 in vivo and presented a protecting effect on the kidney against sepsis-induced injury, indicating that miR-30c-5p could be a novel target for SAKI therapy." (PMID 32892306, 2021). "For example, in cecal-ligation and puncture (CLP)-induced sepsis mice, deletion of TLR4 or TLR2 resulted in significantly decreased levels of pro-inflammatory cytokines (i.e., IL-1β, TNF-α, IL-6, and IL-8) and preserved tissue damages." (PMID 34884813, 2021). "The expression level of MALAT1 was significantly increased in sepsis in vitro, and MALAT1 knockout also reduced serum levels of cTn-I, TNF-α, IL-1β, IL-6, IL-10, IL-17, IFN-γ, C5, and C5a." (PMID 34514170, 2021). "Compared with those in the CLP + DEX group, the levels of TNF-α, IL-1β, and IL-10 increased significantly in the CLP group at 6 h after sepsis induction." (PMID 33981237, 2021). "In order to further explore the potential mechanism of XBJI in treating sepsis, we constructed a comprehensive pathway with five signaling pathways, including MAPK (hsa04010), NF-κB (hsa04064), PI3K-Akt (hsa04151), TNF (hsa04668), and TLR (hsa04620)." (PMID 34938184, 2021). "In the myocardial injury of sepsis model, EA at ST36 lowered CK-MB content in plasma and TNF-α, NO, and MPO contents in cardiac tissues." (PMID 35095910, 2021). "As we commented above, we observed both lower TNFα concentration in brain and expression of ICAM-1 in circulating PMN and pial vessels of mice with sepsis previously treated with cit-AuNP." (PMID 33608025, 2021). "One study also found that while in cases of sepsis and acute respiratory distress syndrome (ARDS) in COVID-19 (−) patients, TNF-α levels normalized rapidly after the primary immune response, it is consistently elevated in COVID-19 (+) patients." (PMID 34575258, 2021). "Macrophages treated with LPS in the presence of CaD expressed significantly lower IL1β, TNFα, and MCP-1, in agreement with a previous study where CaD reduced pro-inflammatory cytokine production in a rat model of sepsis." (PMID 34829669, 2021). "In experimental settings simulating sepsis, LF was shown to lower IL6 and tumor necrosis factor-alpha (TNF-α)." (PMID 34884440, 2021). "By adapting a similar approach to FMF patients, we extracted GM-CSF and TNF-α as biomarkers that discriminate between FMF and sepsis." (PMID 34654467, 2021). "In a study on an animal model of sepsis induction by polysaccharides in C57BL6/J mice, plasma and tissue levels of interleukin-1B (IL-1B) and tumor necrosis factor alpha (TNFα) increased." (PMID 34049594, 2021). "Whole blood from patients with simple sepsis showed a higher expression of TREM-1 and higher levels of IL-6, IL-8, IL-10 and TNF-α upon stimulation with LPS when compared with whole blood from patients with severe sepsis." (PMID 33924130, 2021). "In conclusion, this study showed that GM-CSF and TNF-α can be useful biomarkers for the differential diagnosis of FMF and sepsis when measured in combination." (PMID 34654467, 2021). "We found that TNF-α and NF-kB expressions were lower in the AGO treatment groups than in the sepsis group." (PMID 34177296, 2021). "Cardiac dysfunction and inflammation were observed in sepsis rat, which were characterized by the decrease of LVSP and + dp/dtmax, the increase of LVEDP, − dp/dtmax, cTnI, CK-MB, TNF-α, IL-1β, IL-6." (PMID 34376255, 2021).
Sepsis (continued). "In animal models and in vitro experiments of sepsis, GLP-1 analogs inhibited TNFα and LPS-induced monocyte adhesion, thereby reducing vascular endothelial injury." (PMID 34335269, 2021). "We previously found that SPIONs significantly improved the symptoms of sepsis and liver injury, which was manifested by decreased levels of AST and ALT, decreased TNF-a and IL-6 levels, and increased IL-10 expression." (PMID 34627385, 2021). "During sepsis, LPS-induced HIF-1α activation promotes the production of inflammatory cytokines (including TNF-α, IL-1β, and IL-6) and proapoptotic mediators, resulting in inflammation and apoptosis." (PMID 33567713, 2021). "ELISA showed that the levels of TNF-α, IL-2 and IFN-γ were significantly higher in sepsis group compared with control group (P < 0.05)." (PMID 34536996, 2021). "The levels of sIL-2R, TNF-α, and PCT in the sepsis group were higher than those in the infection group (p < 0.05)." (PMID 34745113, 2021). "Moreover, the ROC curve illustrated that CRP (AUC [95%CI]: 0.755 [0.636–0.874]), TNF‐α (AUC [95% CI]: 0.660 [0.534–0.786]), IL‐1β (AUC [95% CI]: 0.665 [0.549–0.781]), and IL‐6 (AUC [95% CI]: 0.622 [0.507–0.737]) all had potential in discriminating sepsis deaths from sepsis survivors." (PMID 34761437, 2021). "For example, lncRNA PVT1 induces an increase in TNF-α, IL-6, and IL-1β release, and promotes inflammation by regulating TNF-α and JNK/NF-κB signaling pathways in sepsis." (PMID 33710444, 2021). "In the sepsis group, testicular MDA, TNF-α, and IL-6 levels increased and SOD activity decreased compared with the sham group." (PMID 35317115, 2021). "Tumor necrosis factor-α (TNF-α), a key regulator of innate immunity in sepsis-related ALI, was used to stimulate PMNs from healthy C57BL/6J mice in vitro." (PMID 34641966, 2021). "We used Spearman’s correlation analysis to investigate the correlation between clinical disease score (SNAP-II) and levels of BCL-xL, TNF-α, and MMP-index in patients with sepsis." (PMID 34193088, 2021). "The detection of sIL-2R, TNF-α, and PCT in patients with sepsis has good value for the diagnosis of sepsis infection in patients with closed abdominal injury complicated with severe multiple abdominal injuries." (PMID 34745113, 2021). "Pituitary gene expression levels of pro-inflammatory cytokines TNF-α and LIF were higher than normal, but only in the acute phase of sepsis-induced critical illness (1-day sepsis group) and this by more than sevenfold and eightfold, respectively." (PMID 33593393, 2021). "Up-regulation of miR-10a increased ROS, TNF-α, IL-6, and MPO, and downregulation reduced sepsis-induced liver injury." (PMID 34956235, 2021). "Berberine inhibits the expression of TNF-α, IL-6, TLR 4, and TLR 9 in the early phase of sepsis in rats." (PMID 34630083, 2021). "To further explore the proinflammatory effects of MSN in sepsis, we next performed ELISA to measure the effects of MSN silencing on the production of the inflammatory cytokines TNF-α, IL-6, IL-1β, and IL-18 in medium supernatant of HMECs." (PMID 33628853, 2021). "In particular, in LPS-induced-inflammation, PL suppressed leukocytes migration, TNF-α and IL-6 production, NF-κB and regulated extracellular kinases (ERK) 1 and 2 activation, and reduced mortality in sepsis." (PMID 34831393, 2021). "Naringin reduces the release of TNF-α and HMGB1 from LPS-stimulated macrophages and improves survival in a CLP-induced sepsis mice." (PMID 33925132, 2021). "Additionally, in our research we indicate that the evaluated p55 and p75 receptor expression on neutrophils was significantly lowered during the treatment and differed from that in the control group, which may be a subsequent confirmation of the TNF-α involvement in sepsis pathogenesis." (PMID 33672270, 2021). "AE prominently downregulated CXCL-1, CXCL-8, IL-6, TNF-α, Glu1, and HMGB1 mRNA expression but activated IL-1RN, IL-10, Sirt-1, and Nrf-2 mRNA expression in the lung during sepsis." (PMID 34493741, 2021).
Sepsis (continued). "In TNF-α-induced sepsis mice, TG2 inhibited liver injury by downregulating TNF-α-induced expression of pro-death proteases caspase 3 and cathepsin D." (PMID 33672962, 2021). "We showed better reductions in the AST, ALT, serum creatine, and cytokine levels (IL-6, IL-10, TNF-α, IFN-γ, MIP-2, and MCP-1) in both the early and late stages of sepsis." (PMID 34759282, 2021). "Our results showed that either LPS injection or CLP surgery significantly up‐regulated the levels of circulating TNF‐α, IL‐1β, IFN‐γ and IL‐6 in mice, indicating successful establishment of sepsis mouse model." (PMID 33982381, 2021). "While IL-2, CXCL10, and TNF-α contribute to the pathogenesis of sepsis, IL-7, IL-10, GCSF, MCP1, M1P1A are likely elevated as an endogenous attempt to combat sepsis." (PMID 32973504, 2020). "Following sepsis, a number of CD4 T cell extrinsic factors have been found to suppress the activity of CD4 T cells, including the reduced APC function and TNF signaling." (PMID 32903436, 2020). "We found that the levels of IL-6, TNF-α, IL-1β, and MCP-1 were significantly increased at 24 h after sepsis." (PMID 32273831, 2020). "Macrophage depletion by clodronate-containing liposomes in rats with LPS-induced sepsis reduced hepatic IL-1β and TNF-α expression and plasma TNF-α levels." (PMID 32863947, 2020). "Our analysis focused on detecting statistical differences in levels of 6 cytokines associated with cytokine storm (IL-1β, IL-1RA, IL-6, IL-8, IL-18, and TNF-α) between patients with moderate COVID-19, severe COVID-19, and ARDS or sepsis." (PMID 32706339, 2020). "Of these cytokines, tumor necrosis factor-α (TNF-α), interleukin-6 (IL-6) and interleukin-1β (IL-1β), which were produced excessively in the early stage of sepsis, have been found to have potential depressive effects on cardiac function." (PMID 32448150, 2020). "We found that similarly to TNF in serum after CLP, GDF15 levels were significantly increased, in agreement with the findings in sepsis patients." (PMID 32424099, 2020). "Expression of the pro‐inflammatory cytokines TNF‐α, IL‐6, and chemokines like MIP‐2 and KC mRNA in lung tissues was increased in CLP‐induced sepsis and was significantly reduced with miRNA 130b‐3p mimic treatment by 63, 56, 75, and 47.5%, respectively." (PMID 31724825, 2020). "M2 macrophages attenuate sepsis-induced AKI by upregulating IL-10 expression and suppressing TNF-α secretion." (PMID 32733471, 2020). "Thus alternative therapeutic options such as anti-inflammatory drugs could be beneficial as neonatal sepsis is characterized by elevated levels of inflammatory cytokines such as tumor necrosis factor alpha (TNF-α) and interleukin 6 (IL-6) which amplifies the severity of sepsis." (PMID 32076015, 2020). "In comparison with the animals from the control group, those that underwent sepsis had significantly higher levels of serum CRP, TNF-α, TREM, and MDA (p < 0.05)." (PMID 32348434, 2020). "By 24 h after the operation, the Sepsis-G group exhibited higher tumor necrosis factor (TNF)-α, IL-6, and IL-10 gene expressions than the sham group and higher TNF-α and IL-6 expressions than those of the Sepsis-C group." (PMID 32295272, 2020). "Pretreatment of rats from sepsis + cefazolin group with cefazolin led to a significant reduction in the serum levels of CRP, TNF-α, and TREM as compared with rats from sepsis group." (PMID 32348434, 2020). "While TNF-α and IL-1 are released early by the macrophages in inflammation, HMGB-1 is a late mediator in sepsis." (PMID 33584688, 2020). "Compared with other early -phase pro-inflammatory contents, for instance tumor necrosis factor (TNF) and IL-1β, HMGB1 began to appear 8 h and significantly increased after initiation of sepsis." (PMID 33552058, 2020). "On the other hand, in a CLP-induced sepsis model in HSP70.1/3 knockout mice, NF-κB binding/activation, TNFα and IL-6 in lungs and mortality were increased." (PMID 31612270, 2020).